U2AF2 (U2 small nuclear RNA auxiliary factor 2)
Description:
Plays a role in pre-mRNA splicing and 3'-end processing. By recruiting PRPF19 and the PRP19C/Prp19 complex/NTC/Nineteen complex to the RNA polymerase II C-terminal domain (CTD), and thereby pre-mRNA, may couple transcription to splicing. Induces cardiac troponin-T (TNNT2) pre-mRNA exon inclusion in muscle. Regulates the TNNT2 exon 5 inclusion through competition with MBNL1. Binds preferentially to a single-stranded structure within the polypyrimidine tract of TNNT2 intron 4 during spliceosome assembly. Required for the export of mRNA out of the nucleus, even if the mRNA is encoded by an intron-less gene. Represses the splicing of MAPT/Tau exon 10. Positively regulates pre-mRNA 3'-end processing by recruiting the CFIm complex to cleavage and polyadenylation signals.
Synonyms: U2AF65; DEVDFB
Tractability: Small molecule: a structure with a bound ligand is known. PROTAC: UniProt records ubiquitination sites on it; ubiquitination databases record sites on it; its protein half-life has been measured.
Target class: Other nuclear protein
Gene: Protein-coding gene on chromosome 19 (55,654,146 to 55,674,716, forward strand). Ensembl gene ENSG00000063244.
Subcellular location: Nucleus
Subcellular location (Human Protein Atlas): Nuclear speckles; Nucleoplasm
Pathways (Reactome):
Metabolism of RNA: Transport of Mature mRNA derived from an Intron-Containing Transcript; mRNA 3'-end processing; mRNA Polyadenylation; mRNA Splicing - Major Pathway
Disease: Dengue Virus-Host Interactions
Metabolism of proteins: Protein hydroxylation
Gene Ontology:
Molecular function: enzyme binding; molecular function inhibitor activity; pre-mRNA 3'-splice site binding; protein binding; RNA binding; poly-pyrimidine tract binding; nucleic acid binding
Biological process: mRNA splicing, via spliceosome; negative regulation of mRNA splicing, via spliceosome; negative regulation of protein ubiquitination; positive regulation of RNA splicing; mRNA processing; spliceosomal complex assembly; RNA splicing
Cellular component: nuclear speck; nucleoplasm; nucleus; Prp19 complex; spliceosomal complex; U2-type prespliceosome; U2AF complex; commitment complex
Genetic constraint (gnomAD): Loss-of-function variants: 5 observed, 50.23 expected, observed/expected ratio (o/e) 0.0995, 90% interval 0.051 to 0.21. The upper end of that interval is the gene's LOEUF score, 0.21, which puts it in group 1 of 6, group 1 being the genes least tolerant of losing a copy. Missense variants: 219 observed, 675.78 expected, observed/expected ratio (o/e) 0.32, 90% interval 0.29 to 0.36. Synonymous variants: 283 observed, 255.61 expected, observed/expected ratio (o/e) 1.11, 90% interval 1 to 1.22.
Homologues: Orthologues: chimpanzee U2AF2 (100% identical), dog U2AF2 (100% identical), pig U2AF2 (100% identical), guinea pig U2AF2 (99% identical), mouse U2af2 (99% identical), rat U2af2 (99% identical), macaque U2AF2 (99% identical), tropical clawed frog u2af2 (94% identical), zebrafish u2af2a (87% identical), zebrafish u2af2b (86% identical), Drosophila melanogaster U2af50 (64% identical), Caenorhabditis elegans uaf-1 (58% identical), and 1 more. Paralogues in human: UHMK1 (20% identical), CSTF2T (17% identical), CSTF2 (16% identical), RBMX2 (11% identical), ZCRB1 (8% identical).
Diseases named in the same sentence as U2AF2 in open-access papers:
U2AF2 is named in the same sentence as 47 diseases in open-access papers, as found by Europe PMC text mining. Sharing a sentence is not in itself a finding about the gene and the disease. The quoted sentences say what the papers report.
glioma (13 papers, 2015 to 2025). A benign or malignant brain and spinal cord tumor that arises from glial cells (astrocytes, oligodendrocytes, ependymal cells). "Previous studies have linked U2AF2 to malignant progression in various tumors, including prostate cancer, glioma, and melanoma." (PMID 38594783, 2024). "Bioinformatics analysis suggested that U2AF2 was upregulated in IDH-mutated glioma with malignant transformation." (PMID 32894165, 2020). "U2AF2 was also highly enriched in IDH wildtype gliomas, and was associated with decreased survival rates in both TCGA and CGGA datasets." (PMID 32894165, 2020). "Its association with U2AF2 may influence RNA processing and gene expression; however, data on U2AF2’s role in gliomas remain limited." (PMID 41009755, 2025). "In glioma tissues and cells, miR-342-3p is regulated by circ_ARF1, forming a feedback loop composed of U2AF2, ARF1, ISL2, and miR-342-3p, which modulates glioma development." (PMID 36120594, 2022). "U2AF2 acts as an oncogene in several cancers, such as glioma, primary non-small cell lung cancer, and melanoma." (PMID 34439339, 2021). "In glioma, the expressions of U2AF2 and circRNA ARF1 (cARF1) are both up-regulated, and they are associated with decreased survival rates of patients." (PMID 34439339, 2021). "To characterize the expression and functions of U2AF2 in glioma, we searched its expression in both TCGA and CGGA datasets." (PMID 32894165, 2020). "The results showed that U2AF2 was expressed highest in WHO grade IV gliomas and GBM, and lowest in WHO grade II and LGG." (PMID 32894165, 2020). "All qPCR, western blotting, and immunohistochemistry results confirmed higher U2AF2 expressions in glioma tissues than in normal brain tissues, with the highest expression in WHO grade IV gliomas." (PMID 32894165, 2020). "Taken together, these results suggested that U2AF2 promoted glioma angiogenesis via upregulating cARF1 expression in GSCs." (PMID 32894165, 2020). "Our study also focused on the relationship between U2AF2 and glioma, and we showed that U2AF2 was also a novel oncogene in glioma, because it was expressed at higher levels in glioma correlated with poor patient survival." (PMID 32894165, 2020). "Together, these results suggested that U2AF2 was also more highly expressed in gliomas tissues, and was correlated with poor patient survival." (PMID 32894165, 2020). "Taken together, these results showed that the U2AF2/cARF1/miR-342–3p/ISL2 axis regulated glioma tumorigenesis and angiogenesis in nude mice." (PMID 32894165, 2020). "We also showed that both U2AF2 and cARF1 had an oncogenic effect, were overexpressed in glioma, and correlated with poor patient survival." (PMID 32894165, 2020). "Furthermore, U2AF2 bound to and promoted the expression of cARF1, while ISL2 also transcribed the expression of U2AF2, which formed a feedback loop and possibly participated in the malignant transformation of glioma." (PMID 32894165, 2020). "Moreover, we also showed both U2AF2 and cARF1 had oncogenic effects, were overexpressed in gliomas, and correlated with poor patient survival." (PMID 32894165, 2020). "To determine whether U2AF2 promotes glioma angiogenesis, we performed MTS, EDU, Transwell, and tube formation assays and found that the proliferation, invasion, and angiogenesis of hBMECs were decreased after U2AF2-knockdown GSC406-GCM treatment." (PMID 32894165, 2020). "Finally, we performed orthotopic xenografts to determine the effects of the U2AF2/cARF1/miR-342–3p/ISL2 axis in glioma tumorigenesis and angiogenesis in vivo." (PMID 32894165, 2020). "And in TCGA samples, 5.9% of grade 3 gliomas with IDH1 mutation/1p19q co-deletion harbored mutations in U2AF2 while no mutations were found in grade 2 gliomas with the same molecular signature." (PMID 26524630, 2015). "However, while U2AF2 has been implicated in some solid tumours, such as non-small cell lung cancer and glioma, its associations with prostate cancer and metastasis have yet to be elucidated." (PMID 39402324, 2024).
glioma (continued). "In glioma stem cells, circRNA ARF1 is transcriptionally regulated by U2AF2 and circRNF121 in osteoarthritis is regulated by LEF1." (PMID 36072902, 2022). "Our study firstly established a seven-gene signature comprising METTL3, COL18A1, NASP, PHLPP2, TIMP1, U2AF2, and VEGFA with a good capability for predicting survival in glioma." (PMID 34589481, 2021). "Collectively, m6A RNA methylation regulators KIAA1429, METTL16, METTL3, IGF2BP2, and YTHDF, and targets NASP, TIMP1, U2AF2, COL18A1, and VEGFA could serve as oncogenes in glioma, while PHLPP2 is a tumor suppressor." (PMID 34589481, 2021). "Our study established and validated a seven-gene signature comprising METTL3, COL18A1, NASP, PHLPP2, TIMP1, U2AF2, and VEGFA, with a good capability for predicting glioma survival, which may guide therapeutic customization and clinical decision-making." (PMID 34589481, 2021). "Our study therefore identified a U2AF2/cARF1/miR-342–3p/ISL2 feedback loop in GSCs, which promoted glioma angiogenesis, and which may provide novel targets for glioma therapy." (PMID 32894165, 2020). "Additionally, a recent study showed that U2AF2 can directly bind and stabilize circNCAPG, which participates in the nuclear translocation of ras responsive element binding protein 1, thereby activating the TGF-β pathway and promoting glioma progression." (PMID 39495216, 2024).
prostate carcinoma (10 papers, 2009 to 2024). A carcinoma that arises from epithelial cells of the prostate gland. "However, the expression levels of U2AF2 (the gene which encodes U2AF65) do increase in hormone-resistant prostate cancer compared to primary prostate cancer." (PMID 28382513, 2017). "Our study reveals that U2AF2 is highly expressed in prostate cancer patients with biochemical recurrence and worse disease-free survival." (PMID 39402324, 2024). "We also demonstrate that U2AF2 mRNA and protein are both elevated in prostate cancer metastasis relative to localised and benign prostate tissues." (PMID 39402324, 2024). "Further assessment of the role of U2AF2 in advanced, metastatic prostate cancers is needed to test its functional role in prostate cancer metastasis." (PMID 39402324, 2024). "We and other groups revealed that overexpression of various splicing factors including U2AF2 in advanced prostate cancer previously." (PMID 32704143, 2020). "Changes in these proteins were found related to myeloid malignancy (u2af2), clinical monoclonal B-cell lymphocytosis (sf3b1), and prostate cancer (usp39)." (PMID 32823483, 2020). "With the 5-gene prostate cancer metastasis signature panel comprised of U2AF2, RUVBL1, STMN1, HDGF, and FABP4, we further assessed the power of prediction of this gene signature panel in two different, independent public patient datasets (Grasso CS, Nature, 2012; Varambally S CS, Cancer Cell, 2005)." (PMID 39402324, 2024). "Here we demonstrated that the subcellular distribution of U2AF2 was affected in the presence or absence of CRPC-Lnc #6 using combinational analysis of RNA-FISH and immunofluorescence in prostate cancer cells." (PMID 32704143, 2020).
melanoma (6 papers, 2017 to 2024). A malignant, usually aggressive tumor composed of atypical, neoplastic melanocytes. "While ILF2‐OV induced the upregulation of RAD50, U2AF2 knockdown decreased the RAD50 protein levels in ILF2‐OV melanoma cells." (PMID 34709752, 2021). "For example, U2AF2 promotes the alternative splicing of CD44v8-10 in malignant melanoma." (PMID 38462618, 2024). "In addition, the expression levels of CD44v8-10 and U2AF2 are significantly higher in primary melanoma than in dysplastic nevi and are further increased in metastatic melanoma, a crucial milestone during melanoma progression." (PMID 38462618, 2024). "Mechanistically, U2AF2 facilitates CD44v8-10 alternative splicing in malignant melanoma." (PMID 38462618, 2024). "Moreover, ILF2 and U2AF2 mRNA levels had a significant positive correlation in melanoma (primary and metastasis) tumour samples from TCGA SKCM dataset (r = 0.12, p = .008)." (PMID 34709752, 2021). "The results showed that ILF2 interacts with U2AF2 in the nucleus of metastatic melanoma cell lines." (PMID 34709752, 2021). "Additionally, stage III melanoma patients with high ILF2 mRNA expression had significantly higher U2AF2 mRNA levels compared to patients with low ILF2 mRNA expression (p < .05)." (PMID 34709752, 2021). "In addition, U2AF2 is significantly increased in melanoma progression and participates in brain metastasis." (PMID 32894165, 2020). "In primary melanoma, a close correlation exists between splicing factors, such as ESRP1, ESRP2, PTBP1, and U2 snRNP auxiliary factor (U2AF2), and the expression of CD44v6." (PMID 38462618, 2024). "A significant upregulation of U2AF2 mRNA levels was observed in primary melanoma compared to normal skin (p < .05) and nevus tissues (p < .0001) using GSE3189 microarray dataset." (PMID 34709752, 2021).
non-small cell lung carcinoma (6 papers, 2020 to 2024). A group of at least three distinct histological types of lung cancer, including non-small cell squamous cell carcinoma, adenocarcinoma, and large cell carcinoma. "U2AF2 expression was significantly upregulated in primary non-small cell lung cancer and was associated with metastasis, advanced tumor stages, poor survival, and recurrence." (PMID 32894165, 2020). "U2AF2 expression is significantly increased in lung cancer and is closely related to metastasis, advanced disease stage, recurrence and poor survival in non-small cell lung cancer patients." (PMID 38594783, 2024). "OTUB2 is linked to the Akt/mTOR pathway by targeting U2AF2, unfortunately, the molecular mechanism of U2AF2 in non-small cell lung cancer is still unclear." (PMID 35309903, 2022). "Similarly, in non-small cell lung cancer, OTUB2 could bind to U2AF2 and deubiquitinate it, making U2AF2 more stable, promoting the Warburg effect of tumors through the AKT/mTOR signaling pathway." (PMID 38819228, 2024).
colorectal cancer (5 papers, 2012 to 2026). A primary or metastatic malignant neoplasm that affects the colon or rectum. "In colorectal cancer, LINC00665 can interact with U2AF2, enhance the binding between U2AF2 and CTNNB1 mRNA, and increase the stability of CTNNB1 mRNA, thereby further activating the Wnt/β-catenin signaling pathway and stimulating the proliferation and invasion of colorectal cancer cells." (PMID 35563845, 2022). "Interestingly, we found that two enriched motifs, SRSF2 and U2AF2, were previously reported to be highly involved in AML progression through aberrant splicing regulation and another motif, PTBP1, was shown to play an important role in breast and colorectal cancers." (PMID 29665865, 2018).
lung carcinoma (4 papers, 2019 to 2025). "Although the relationship of U2AF2 with tumorigenesis is poorly studied, certain reports have demonstrated cancer-associated mutations in this SF, and it has also been found upregulated in lung cancer and highly metastatic hepatocellular carcinoma." (PMID 31561558, 2019). "Lnc ASMTL-AS1 binds to U2AF2, stabilizing SAT1 mRNA expression and promoting ferroptosis in lung cancer cells." (PMID 40191204, 2025). "In lung cancer, OTUB1 triggered lung cancer development by inhibiting RAS monoubiquitination; OTUB2 stabilized U2AF2 through the AKT/mTOR signaling pathway to promote the Warburg effect and tumorigenesis; and OTUD3 stabilized GRP78 to augment the malignancy." (PMID 40469292, 2025). "For example, lnc ASMTL-AS1 binds to U2AF2, stabilizing SAT1 mRNA expression and promoting ferroptosis in lung cancer cells." (PMID 40191204, 2025).
myelodysplastic syndrome (4 papers, 2016 to 2023). A clonal hematopoietic disorder characterized by dysplasia and ineffective hematopoiesis in one or more of the hematopoietic cell lines. "U2AF2 (U2 small nuclear RNA auxiliary factor 2) is a component of the spliceosome complex that appears mutated with low frequency in myelodysplastic syndromes, but to the best of our knowledge its role in EMT regulation has not been tested." (PMID 37298909, 2023).
developmental delay (3 papers, 2024). "De novo mutations affecting the pre-mRNAsplicingfactor U2AF2 are associated with developmental delays and intellectualdisabilities, yet the molecular basis is unknown." (PMID 39388459, 2024).
viral infection (3 papers, 2021 to 2024). "Interestingly, U2AF2 acetylation was also remarkably reduced in the cells subjected to serum starvation, endoplasmic reticulum (ER) stress (induced by tunicamycin), viral infection [poly (I:C)], or DNA damage stress (induced by cisplatin)." (PMID 39495216, 2024).
breast carcinoma (2 papers, 2020 to 2024). "Through bioinformatics analysis, U2AF2 was found to be highly expressed in breast cancer, indicating a poor prognosis." (PMID 38594783, 2024). "U2AF2 is upregulated in various cancers but has rarely been studied in breast cancer." (PMID 38594783, 2024). "Bioinformatic analysis revealed that U2AF2 expression was increased in breast cancer." (PMID 38594783, 2024).
renal fibrosis (2 papers, 2024 to 2025). A final common manifestation of a wide variety of chronic kidney diseases characterized by glomerulosclerosis and tubulointerstitial fibrosis. "Together, these data support that SIRT4-mediated deacetylation of U2AF2 at K413 is an important step in SIRT4-induced renal fibrosis." (PMID 39495216, 2024). "Compared to that in WT mice, the acetylation level of U2AF2 was increased, but renal fibrosis was reduced in S4KO mice after UUO surgery." (PMID 39495216, 2024). "To determine whether S4KO alleviates renal fibrosis by upregulating the acetylation of U2AF2 in mouse kidney, we crossed Cdh16-cre/ERT2×U2af2flox/flox (U2af2-/-) with Sirt4-/- mice to generate DKO mice and then performed UUO surgery." (PMID 39495216, 2024). "Additionally, a recent study shows that Sirt4 could also translocate into nucleus, which mediates deacetylation of U2AF2 to modulate renal fibrosis." (PMID 40842073, 2025).
triple-negative breast carcinoma (2 papers, 2022 to 2024). An invasive breast carcinoma which is negative for expression of estrogen receptor (ER), progesterone receptor (PR), and human epidermal growth factor receptor 2 (HER2). "From all the RBPs investigated, seven were differentially expressed and upregulated (AGO2, EIF4A3, ELAVL1, IGF2BP2/3, LIN28B, and U2AF2), showing that these genes have an important role in triple-negative breast cancer development." (PMID 35805051, 2022).
acute myeloid leukemia (1 paper, 2022). Acute myeloid leukemia (AML) is a group of neoplasms arising from precursor cells committed to the myeloid cell-line differentiation. "For the LIOTs, despite low indel frequency (below 3%), significantly detectable indels were found in the exon of nine cancer genes, such as U2AF2 and NKTR causing Acute myeloid leukemia (AML)." (PMID 35831290, 2022).
Alzheimer disease (1 paper, 2022). A progressive, neurodegenerative disease characterized by loss of function and death of nerve cells in several areas of the brain leading to loss of cognitive function such as memory and language. "For example, we found that levels of ADAR, XRCC6 and SBDS were reduced in 5 of 7 Alzheimer’s disease samples and levels of DDX5, U2AF2, ILF3 were reduced in 4 of 7 Alzheimer’s disease NPC vasculature samples by greater than 50%." (PMID 36196083, 2022). "However, many of the RBPs under-expressed in Alzheimer’s disease HPC vasculature do play important roles in neurological health and neurodegenerative diseases including ADAR, XRCC6, U2AF2 and ILF3." (PMID 36196083, 2022).
liver abscesses (1 paper, 2022). "While in humans, U2AF2 has been associated with alternative splicing in transformed cells, the ortholog EhU2AF2 has been associated with virulence because it is overexpressed in amoebas recovered from liver abscesses." (PMID 35782149, 2022).
liver cancer (1 paper, 2022). An epithelial or non-epithelial malignant neoplasm that arises from the liver. "To validate this hypothesis, we used RNA interference to knockdown hnRNPC and U2AF2 expression in liver cancer cells, after which miR-21-5p and isomiR-21-5p | ±1 expression levels were measured." (PMID 35729324, 2022).